CHMP4B (charged multivesicular body protein 4B)
Diseases named in the same sentence as CHMP4B in open-access papers:
CHMP4B is named in the same sentence as 34 diseases in open-access papers, as found by Europe PMC text mining. Sharing a sentence is not in itself a finding about the gene and the disease. The quoted sentences say what the papers report.
cataract (8 papers, 2014 to 2023). Partial or complete opacity of the crystalline lens of one or both eyes that decreases visual acuity and eventually results in blindness. "Of interest, the D129V mutation in CHMP4B associated with the development of cataracts lies adjacent to the minimal interaction region of CHMP4B with ALIX (i.e., between amino acids 205 and 224)." (PMID 34440370, 2021). "In support of this model, polymorphisms in the ESCRT-III proteins CHMP2B and CHMP4B are associated with dementia and cataracts, respectively, both of which are associated with mutations in lamin A/C37,43-45." (PMID 30139939, 2018). "Interestingly, the mutation in CHMP4B D129V found in cataract patients was shown to abolish its localization to micronuclei compared to the wild-type protein." (PMID 24741567, 2014). "Interestingly, the gene that encodes CHMP4B protein, CHMP4B, is found mutated in autosomal dominant cataracts." (PMID 24741567, 2014). "Mutations in CHMP4B (charged multivesicular body protein 4B), a gene encoding a key component of the ESCRT (endosomal sorting complex required for transport), are associated with autosomal dominant cataracts." (PMID 37034386, 2023). "In addition, lens methylation profiles at cataract-related loci include Chmp4b, Col4a1–Col4a2, and Lss may help studies of aging human lenses and formation of cataracts." (PMID 36698218, 2023).
hepatocellular carcinoma (5 papers, 2018 to 2023). A malignant tumor that arises from hepatocytes. "As an autophagy-related lncRNA, PLBD1-AS1 has been demonstrated to be significantly correlated with the prognosis of hepatocellular carcinoma and may be linked to TP53BP1 and CHMP4B." (PMID 37470034, 2023). "In addition, CHMP4B siRNA depletion in hepatocellular carcinoma cells reduced cell proliferation and sensitized cells to doxorubicin." (PMID 29954076, 2018). "In addition to human tumor samples that show largely upregulation of CHMP4B expression in various cancer types, CHMP4B expression was also found to be high in human patient hepatocellular carcinoma tissue compared with adjacent normal tissue and high CHMP4B expression correlated with poor survival." (PMID 29954076, 2018). "The silence of both CHMP4B and Vps4A decrease the level of exosomal β-catenin, thus dampening β-catenin signing so as to prevent epithelial–mesenchymal transition (EMT) in hepatocellular carcinoma (HCC)." (PMID 34661500, 2021).
viral infection (4 papers, 2021 to 2024). "Previous research has explored that when countering viral infection, genes related to exosome trafficking, such as Charged Multivesicular Body Protein 4B (CHMP4B), TSG101, and Annexin A2 (ANXA2) are activated in pDCs." (PMID 33665710, 2021). "The protein levels of these ESCRT subunits (HRS, VPS28, VPS25, CHMP2B, CHMP4B, CHMP7, VPS4A and ALIX) in the VRC were significantly increased by the viral infection in a dose-dependent manner." (PMID 35120190, 2022). "Initially, we posited that PEDV might interact with ALIX through viral proteins and that ALIX directly interacts with CHMP4B through its Bro1 domain, thus directly forming ESCRT-III and recruiting the ESCRT system to complete the virus infection cycle." (PMID 38489378, 2024).
congenital cataracts (3 papers, 2020 to 2023). "Lens-specific Chmp4b-deficient mice develop congenital cataracts with severe cellular damages, probably due to various dysfunctions in CHMP4B-related pathways." (PMID 37034386, 2023).
Alzheimer disease (2 papers, 2025). A progressive, neurodegenerative disease characterized by loss of function and death of nerve cells in several areas of the brain leading to loss of cognitive function such as memory and language. "Roles for CHMP4B in the autophagy-lysosomal pathway in Alzheimer's disease have also been reported." (PMID 41488750, 2025).
endometrial carcinoma (2 papers, 2024 to 2025). A malignant tumor arising from the epithelium that lines the cavity of the uterine body. "CHMP4B, which reverses gasdermin D-mediated pyroptosis in endometrial cancer by remodeling cell membranes, was also associated with adverse OS in the TCGA-UCEC dataset when mRNA expression was high." (PMID 38562170, 2024). "Notably, our results revealed that cleaved gasdermin D-high/CHMP4B-low endometrial cancer was significantly associated with endometrioid carcinoma, FIGO grades 1–2, and favorable RFS." (PMID 38562170, 2024). "Immunohistochemistry was used to assess the expression of four pyroptosis-associated molecules (NLRP3, cleaved caspase-1 p20, cleaved gasdermin D, and CHMP4B) in 351 patients with endometrial cancer, and their associations with clinical, pathological, and survival outcomes were analyzed." (PMID 38562170, 2024). "This theoretical perspective offers valuable insights into reconciling the divergent prognostic implications of high cleaved caspase-1 p20, which indicates a worse prognosis, with the more favorable outlook associated with high cleaved gasdermin D and low CHMP4B expressions in endometrial cancer." (PMID 38562170, 2024). "To evaluate the impact of cleaved gasdermin D-mediated pyroptosis unhindered by CHMP4B, we compared survival outcomes between cleaved gasdermin D-low/CHMP4B-high and cleaved gasdermin D-high/CHMP4B-low endometrial cancers." (PMID 38562170, 2024). "To investigate the potential interaction between cleaved gasdermin D and CHMP4B, we conducted a comparative analysis between cleaved gasdermin D-high/CHMP4B-low endometrial cancer and cleaved gasdermin D-low/CHMP4B-high endometrial cancer." (PMID 38562170, 2024). "To evaluate the consequences of cleaved gasdermin D-mediated pyroptosis without CHMP4B-mediated membrane repair, we analyzed the clinicopathologic characteristics of cleaved gasdermin D-low/CHMP4B-high and cleaved gasdermin D-high/CHMP4B-low endometrial cancer." (PMID 38562170, 2024). "In our previous study, CHMP4B and VPS4A mitigate GSDMD-mediated pyroptosis by promoting cell membrane remodeling in endometrial carcinoma." (PMID 40538398, 2025).
lung carcinoma (2 papers, 2026). "RESULTS: Eight PANoptosis-related genes (DAPK2, CAV1, PDK4, IL3RA, NOTCH1, CHMP4B, IRAK1, and SFN) were identified as being significantly associated with lung cancer." (PMID 41760846, 2026). "In lung cancer patients, elevated c-Jun activation, HMGCS1 expression, cholesterol content and PM CHMP4B correlate with reduced anti-PD-1 immunotherapy efficacy." (PMID 42248910, 2026).
melanoma (2 papers, 2015 to 2021). A malignant, usually aggressive tumor composed of atypical, neoplastic melanocytes. "The ASIP region is one of four known melanoma-susceptibility regions and includes the four genes (RALY, EIF2S2, CHMP4B and ASIP)." (PMID 26083354, 2015).
Age-related nuclear cataract (1 paper, 2024). A type of age-related cataract that primarily affects the nucleus of the lens. "Variants in many genes underlying inherited forms of cataract (e.g., BFSP1, LIM2, MIP, and CHMP4B) have been shown to exhibit tentative association with age-related nuclear cataract." (PMID 38927721, 2024).
brain trauma (1 paper, 2020). "However, the role of CHMP4B has not been explored in brain trauma." (PMID 32585748, 2020).
colon cancer (1 paper, 2023). "The second gene where the adjusted p-value between the cfDNA of colon cancer patients and the gDNA of colon cancer tissue samples was somewhat higher was CHMP4B (adjP = 0.02)." (PMID 37628686, 2023).
deafness (1 paper, 2020). An inherited or acquired condition characterized by the complete loss of the ability to hear from one or both ears. "Interestingly, among others PSMC3 was shown to interact with CHMP4B (MIM 610897), ACTG1 (MIM 102560) and GJB6 (MIM 604418) involved in cataract and deafness." (PMID 32500975, 2020).
gastric cancer (1 paper, 2025). A primary or metastatic malignant neoplasm involving the stomach. "Prognostic association specific to cancer: Survival analysis indicated that elevated CHMP4B expression was correlated with extended survival in OV patients, whereas it was significantly linked to unfavorable prognosis in gastric cancer STAD." (PMID 40230849, 2025).
intracerebral hemorrhage (1 paper, 2022). A cerebrovascular disorder characterized by bleeding into one or both cerebral hemispheres including the basal ganglia and the cerebral cortex. "An in vitro study reported that Chmp4b may play a role in neuronal apoptosis and could be related to brain damage following intracerebral hemorrhage." (PMID 35655748, 2022).
kidney stones (1 paper, 2025). "Overexpression of CHMP4B attenuates cell death and reduces the severity of kidney stones." (PMID 40384863, 2025). "Our study found that CHMP4B expression levels were elevated in a mouse model of Gly-induced kidney stones but not sufficient to resist GSDMD-mediated pyroptosis." (PMID 40384863, 2025).
Microcornea (1 paper, 2010). A congenital abnormality of the cornea in which the cornea and the anterior segment of the eye are smaller than normal. "For example, mutations in multiple genes have been associated with cataract plus microcornea (e.g., MAF, CRYAA, and GJA8), posterior polar cataract (e.g., PITX3, EPHA2, CHMP4B, and NF2), or sutural cataract (e.g., BFSP2, CRYAB, and NHS)." (PMID 21042563, 2010).
tumor (15 papers, 2018 to 2026). "Evidently, various reports have shown the elevated expression of USP22, CBX6, NRAGE, ACTL6, and CHMP4B genes correlate with larger tumor size, advanced tumor stages, poor prognosis and short survival time of patients in LIHC." (PMID 31490960, 2019). "Differential expression analysis revealed that CASP4, CHMP4B, ELANE, IL-1A, and TNF were significantly upregulated in tumor samples (p < 0.05)." (PMID 40538398, 2025). "We observed selective activation of the ESCRT-III effector proteins CHMP2A and CHMP4B in both human and mouse CRC tumor cells." (PMID 38898209, 2024). "Furthermore, immune infiltration analysis suggested roles for CHMP4B and IRAK1 in modulating the tumor immune microenvironment." (PMID 41760846, 2026). "Notably, CHMP4B and IRAK1 showed distinct expression patterns in different immune cell populations, indicating their potential roles in shaping the tumor immune microenvironment." (PMID 41760846, 2026). "Ablation of GSDMD reduced the number of tumor cells that harbor aggregated CHMP2A and CHMP4B." (PMID 38898209, 2024). "We reason that this could be due to the observed accumulation of aggregated CHMP2A and CHMP4B proteins, members of the ESCRT membrane repair machinery, in the membrane of both human and mouse CRC tumor cells, that were decreased upon ablation of GSDMD in mice." (PMID 38898209, 2024).
infection (13 papers, 2011 to 2025). The state of being infected such as from the introduction of a foreign agent such as serum, vaccine, antigenic substance or organism. "The number of LdLPVs in ALIXKD that were CHMP4b positive was significantly lower at 24, 48, and 72 hrs post-infection." (PMID 40956840, 2025). "Approximately 21% to 26% of LdLPVs positively displayed CHMP2B-mCherry or CHMP4B-mCherry at 24,48 and 72 hours after infection." (PMID 40956840, 2025). "While approximately 33% of LdLPVs in shCTRL and in TSG101KDs were always CHMP4B-mCherry post-infection, less than 18% LdLPVs in ALIXKDs were positive for CHMP4B-mCherry." (PMID 40956840, 2025). "Chmp4B RNA was unchanged during the course of the infection, while Chmp2B mRNA was significantly increased at 12 dpi (lower middle)." (PMID 30837340, 2019). "Cells depleted for Chmp4B showed similar infection rates and bacterial load as control cells, indicating that Chmp4B is not required for bacterial growth." (PMID 27774439, 2016). "We next examined the levels of HCV Core and the infectivity of HCV in the culture supernatants as well as the level of HCV RNA in the TSG101, Alix, Vps4B, or CHMP4b stable knockdown RSc cells 97 h after HCV-JFH1 infection at an MOI of 0.1." (PMID 21264300, 2011). "To determine whether the ESCRT pathway might still play an important role in HPIV1 replication, we decided to test whether Chmp4 knock-down yielded a detectable phenotype during HPIV1 infection since the C proteins and Chmp4b bind at the same site in the Bro1 domain of Alix." (PMID 23527201, 2013). "Surprisingly, the main ESCRT-III component CHMP4b was massively recruited to the PV, and its expression level was upregulated upon BMDC infection by T. gondii." (PMID 35309938, 2022). "Deletion of a component of ESCRT-III, the charged multivesicular body protein 4B (CHMP4B), in HeLa cells followed by siRNA knockdowns of CHMP4A and CHMP4C and infection with HSV-1 resulted in a similar phenotype as deletion of the ESCRT-III adaptor ALIX." (PMID 35062219, 2021). "The roles of Alix, Chmp4b, and the viral C proteins in HPIV1 infection remain incompletely understood, but a preliminary model can be proposed." (PMID 23527201, 2013). "We showed that silencing of essential proteins of the ESCRT-0 (Hrs), -I (Tsg101), and -III (Chmp4B) machineries had no impact on primary infection, nor on the progeny collected." (PMID 27774439, 2016). "Similarly in macrophages, pathogen infection induces lysosomal damage and was shown to result in relocalization of LRRK2 to the damaged lysosome where it phosphorylated Rab8A, and this recruited the ESCRT-III component CHMP4B that orchestrates the repair of lysosome damage." (PMID 38091401, 2023). "There is a mild defect in virus spread in the presence of dominant negative CHMP4B and CHMP6, quantitated via immunocytochemistry of cells expressing immediate early proteins following low MOI infection, but the effect of dominant negative VPS4 on spread was not analysed." (PMID 38900818, 2024).
cancer (10 papers, 2018 to 2025). A tumor composed of atypical neoplastic, often pleomorphic cells that invade other tissues. "Accordingly, we found that cleaved gasdermin D-high/CHMP4B-low cancer was significantly associated with favorable RFS (log-rank p = 0.021) and tended to have a favorable OS (log-rank p = 0.128)." (PMID 38562170, 2024). "Of note, although aneuploidy is usually to be a hallmark of cancer, aneuploid mESCs did exhibit impaired differentiation capacity, which was also confirmed in our ishUbe2s/Chmp4b-mESCs." (PMID 35147915, 2022). "Given this link between CHMP4B and micronuclei surveillance and clearance, it will be important to evaluate the role of CHMP4B in other diseases states associated with micronuclei formation, including chromosomal instability seen in some cancers." (PMID 34440370, 2021). "The main types of copy number variations of pyroptosis genes in pan-cancer were heterozygous amplifications and deletions, among which the CNVs of CHMP4B, CHMP4C, and IL6 in most tumors were heterozygous amplifications." (PMID 36090967, 2022). "Our VPS4KD data imply the existence of a similar mechanism; hence, the accumulation of CHMP7 and CHMP4B at micronuclei observed in unperturbed cancer cells implies the normal balance between ESCRT-III assembly and disassembly is impaired and/or is not regulated by VPS4 (VPS4-independent pathway)." (PMID 30988276, 2019). "Similarly, some progressors (CHMP4B, CSTF1, and LSM14B) and suppressors RBPs (ATP5F1A, GTF2E2, RTF1, ELAC2, LRRC47, and MRM3) have never been associated with COAD or READ, but present oncogenic properties in other cancer types." (PMID 37384253, 2023).
CHMP4B also shares sentences with these, for which no sentence is quoted: autosomal dominant cataract (2 papers); COVID-19 (2); frontotemporal dementia (2); breast carcinoma (1); calcium oxalate kidney stone (1); dementia (1); endometrioid carcinoma (1); Frontotemporal dementia linked to chromosome 3 (1); genetic disease (1); glioma (1); liposarcoma (1); lymph node metastasis (1); Posterior polar cataract (1); synovial sarcoma (1); type 2 diabetes (1).